YAP1 (Yes1 associated transcriptional regulator)
Diseases named in the same sentence as YAP1 in open-access papers (continued):
Sharing a sentence is not in itself a finding about the gene and the disease.
cancer (continued). "It has been shown that both YAP1 and KRAS have a common biding site which is the E2F transcription factor and that in the absence of KRAS signaling YAP1 functionally replaces KRAS in KRAS-dependent cancer cells." (PMID 29850494, 2018). "Besides, tankyrase inhibitor sensitized cancer cells to endothelial growth factor receptor (EGFR) inhibition through stabilizing AMOT and inhibiting YAP1 signaling in lung cancer cells." (PMID 29650031, 2018). "On the contrary, the subgroup of 25% of ccRCC patients in whom cytoplasmic presence of YAP1 in cancer cells was observed showed significantly shorter OS (median = 26.8 months) than patients without cytoplasmic YAP1 presence (median undefined)." (PMID 29850494, 2018). "We test the hypothesis that YAP1/∆Np63α signaling is targeted and suppressed by SFN as a mechanism of cancer prevention/therapy." (PMID 29088716, 2017). "Both YAP1 and HSPC111 were up-regulated in cancer cell lines, compared with GES1 cells." (PMID 29113304, 2017). "The mechanism of YAP1-promoted resistance includes activation of the receptor tyrosine kinase AXL, the apoptosis inhibitor Survivin (BIRC5) genes, and autophagy depending on different drugs in different cancers." (PMID 27911857, 2017). "This suggests that the oncogenic potential of YAP1 may arise through the epigenetic silencing of RASSF1A and the deregulation of YAP1 in cancer." (PMID 29179447, 2017). "YAP1 expression is elevated in a number of human malignancies and its expression has been suggested as a negative prognostic factor for cancer." (PMID 29228705, 2017). "YAP1 reprograms Lgr5+ cryptic stem cells by inhibiting the Wnt homeostatic program while inducing a regenerative program that includes the activation of EGFR signaling, which drives cancer initiation." (PMID 29312609, 2017). "YAP-TEAD signaling was previously shown to activate the promoters of OCT-3/4 and NANOG stem cell markers, and recent results showed overexpression of CD90, a cancer stem cell marker, in HCC cell lines in which YAP1 expression was stimulated as a consequence of TAZ inhibition." (PMID 27359056, 2016). "This revealed that WWTR1 and YAP1 (not shown) were highly expressed in most cancer cell lines, with the exception of low expression in blood cancers." (PMID 27184927, 2016). "AGR2 expression also results in YAP1 activation and induced AREG expression in human cancer cells." (PMID 27764193, 2016). "Here, we comprehensively mapped YAP1 chromatin binding genome-wide in two different cancer cell lines and in non-transformed cells, enabling an unbiased assessment of the sequence features that direct YAP1-mediated regulation." (PMID 26295846, 2015). "Here we investigated its genomic binding landscape in YAP1-activated cancer cells, as well as in non-transformed cells." (PMID 26295846, 2015). "Our findings therefore have important implications for a broad range of research efforts aimed at decoding and eventually manipulating YAP1 biology in cancer settings, regenerative medicine, and possibly also noncancer human diseases." (PMID 25601544, 2015). "Our result supported that the positive YAP1 expression could indicate both poor OS and poor DFS in patients with carcinomas." (PMID 26263504, 2015). "As a consequence, there is no direct evidence about the oncogenic role of endogenous YAP1 in the context of cancer cells carrying the 11q22 amplification event." (PMID 24810989, 2014). "This is intriguing in light of reports indicating a tight interaction between the WNT-TCF and HIPPO-TEAD/YAP pathways: YAP1 is regulated by the WNT-TCF pathway, the HIPPO-YAP1 pathway regulates WNT signaling, and YAP1 is essential for β-CATENIN-dependent cancers." (PMID 24920608, 2014). "Targeting on molecules involved in nAChR-signaling and Hippo pathway such as YAP1 and PKC may represent a promising strategy for the treatment of smoking related cancers." (PMID 24621512, 2014).
cancer (continued). "Because YAP1 and WWTR1 are located at the crossroads of adhesion, GPCR, RTK and stem-cell signaling network, cancer genomics of the FAT signaling cascades could be applied for diagnostics, prognostics and therapeutics in the era of personalized medicine." (PMID 23076869, 2012). "However, due to the lack of accessible binding pockets in YAP1 for small molecule compounds, drug development to direct target YAP1 is yet not successful for the treatment of human cancer." (PMID 39827153, 2025). "Additionally, we examined the effects of AURKA inhibition with alisertib and created a dominant-negative YAP1 Ser397 mutant to assess its impact on cancer stem cell features." (PMID 38467828, 2024). "Interestingly, in the group with high RELA expression, patients with cancer with high YAP1 expression had significantly shorter survival times, but not in the group with low RELA expression." (PMID 38164185, 2024). "Although the relationship between VHL and YAP1 in RCC progression is not clear, YAP1 could be associated with HIF-1α (a major downstream target of VHL) in cancer cells under hypoxic conditions to induce VEGF-A transcription." (PMID 39123485, 2024). "Therefore, disrupting the interaction between YAP1 and TEAD may hold promise as an effective strategy for cancer therapy." (PMID 37375228, 2023). "In addition, ovatodiolide, which suppresses YAP1-modulated cancer stem cell phenotypes in highly malignant HCC, could prevent the polarization of M2 TAMs through YAP1 oncogenic pathways." (PMID 35672802, 2022). "Lamin-A, C profiles appear strikingly similar to those for the mechanosensitive factors Vinculin, Yap1, and Piezo1, whereas datasets for lamin-B1 align with and predict regulation by the cell cycle transcription factor, FOXM1, and further predict poor survival across multiple cancers." (PMID 35719698, 2022). "Thus, YAP1 and TAZ may be utilized as an indicator of chemo- or radiotherapy response to select the optimal treatment for cancer patients." (PMID 36289774, 2022). "Although YAP1 and TAZ are equivalently placed as downstream effectors of the Hippo pathway with oncogenic roles in human cancers, several lines of evidence indicate that YAP1 and TAZ are not functionally reductant and exert distinct functions depending on the cancer types involved." (PMID 35930163, 2022). "However, several mechanisms of Wnt/YAP1-induced cancer stemness have not yet been demonstrated in LCSCs." (PMID 35672802, 2022). "Not all cancers with YAP1 activation are responsive to the inhibition of YAP1 alone." (PMID 34685695, 2021). "In the human mammary MDA-MB-231 cancer cells, the premature polyadenylation of MAGI3 produces a truncated protein depleted of PDZ2-PDZ5 (MAGI3pPA) that acts in a dominant-negative manner to prevent full-length MAGI3 from interacting and impairing YAP1 nuclear translocation." (PMID 34503076, 2021). "An interesting question is why YAP1 amplification is not a more frequent event in human cancers." (PMID 34150758, 2021). "Whether YAP1/TAZ and TEADs are critical for the continued growth of already established tumors is still a largely unanswered question critical to successfully targeting YAP1/TAZ–TEAD in cancer." (PMID 34685695, 2021). "The protein–protein interaction analysis also resulted in an association between other EMT-related genes, including N-cadherin with YAP1, CD44, and α-SMA, suggesting that these genes may play a dual role in both the activation of CAFs and stemness in carcinoma cells." (PMID 34680267, 2021). "Furthermore, YAP1 or WWTR1 amplifications occur in approximately 19% of HNSCC (YAP1–5.5%, WWTR1–14.3%), which puts it among the top five cancers with the highest amplification of these genes amongst 33 cancer types." (PMID 32990596, 2020). "Our CHX chase assays further demonstrated that ERK2 but not ERK1 could stabilize YAP1 expression in cancer cells." (PMID 31848326, 2019).
cancer (continued). "In our cell model, LIF/LIFR-rich cancer cells (cLIF) expressed lower levels of phosphorylated YAP1 as well as total YAP1 protein, leading to the hypothesis that LIF regulates LIFR–YAP1 signaling to promote NPC invasive phenotypes." (PMID 30504771, 2018). "However, a very recent study has shown that VP demonstrate activity against cancer cell lines that is independent of YAP1 and instead dependent on the ability to induce high MW protein oligomers, in particular STAT3 and SQSTM1." (PMID 30263014, 2018). "Importantly, siRNA-mediated YAP1 knockdown alone did not have a significant effect on anoikis rates in cancer cells." (PMID 28827520, 2017). "We demonstrate that this finding is not just limited to a cellular situation where YAP1 is amplified since we observe a similar predominant enrichment of TEAD motifs in YAP1 peak regions in a YAP1-activated NCI-H2052 cancer cell line as well as in non-transformed IMR90 cells." (PMID 26295846, 2015). "Taken together, these findings indicate that YAP1 binding to enhancers, as well as the presence of double TEAD motifs with a 3bp spacer, are general features of YAP1-mediated transcription in YAP1-activated cancer as well as non-transformed cells even though targeted enhancers can largely differ." (PMID 26295846, 2015). "Recently, miR-375 has been found to suppress core hallmarks of cancer by targeting several important genes like AEG-1, YAP1, IGF1R and PDK1.The target genes regulated by miR-375 may function spatiotemporally or in cooperation with each other in different cellular processes." (PMID 26642205, 2015). "Additionally, recent approaches exploring small molecule inhibitors to disrupt the YAP1-TEAD interaction, such as Verteporfin, have demonstrated promising preclinical antitumor activity, but have shown limited clinical efficacy due to off-target toxicity in human cancers." (PMID 40307228, 2025). "Our findings on the critical functions of Yap1 and Cox2 signaling circuits in the adaptive stress response and the efficacy of co-targeting Yap1 and Cox2 in late-stage PDAC led us to further explore whether the Yap1-Cox2 signaling circuit is operative in other cancer types besides PDACs." (PMID 39468013, 2024). "In 2019, research revealed that verteporfin, by blocking YAP1 (a transcriptional regulator of genes that promote cell survival and proliferation) and STAT3, might become an appropriate medicine for targeted therapy of cancer stem cells (CSCs), which may be the promise of targeted therapy for BC." (PMID 37124495, 2023). "In addition, other aspects of Yap1 isoforms such as possession of distinct WW domains between them could also be therapeutically exploited and potentially prove beneficial for the treatment of NSCLC as well as other cancers." (PMID 35014181, 2022). "Thus, behind the scenes of mutual exclusion for SOX2 amplification and YAP1 amplification of these patients in this study, there lies a unique unknown molecular mechanism of ESCC tumorigenesis, distinguished from other cancer types, which needs further investigation." (PMID 35548450, 2021). "Therefore, YAP1 may participate in cancer glycosylation metabolism through O-GlcNAcylation and OGT expression in order to maintain the abnormal proliferation and survival of cancer cells." (PMID 32390875, 2020). "However, in CTCs, when proliferation is not the major task of cancer cells, YAP1 may interact with other factors and regulate other functions, for example survival against anoikis." (PMID 32292505, 2020). "On the contrary, the loss of Thr495 phosphorylation by the phosphorylation-defective mutant DUB3 T495A, the cancer-related mutant DUB3 D496H and CK2 inhibition failed to deubiquitinate and stabilize YAP1 effectively." (PMID 39827153, 2025). "In the majority of YK-1–3 cases, the cytoplasm of cancer cells was low or negative for MST2 (28 of 40 cases) and weakly positive for YAP1 (32 of 40 cases)." (PMID 38444414, 2024).
cancer (continued). "The miR-484 is a key regulator in common cancers and non-cancer diseases, targeting inflammation, apoptosis, and mitochondrial function-related mRNAs (SMAD7, Fis1, YAP1, etc.), and plays an important role in fighting disease." (PMID 37504299, 2023). "Third but not least, YAP1 and TAZ have been shown to exert opposite functions in specific cancer types pending further clarification." (PMID 36289774, 2022). "For example, in liver tumors, the absence of Yap1, which is essential for CSC self-renewal and tissue-specific CSC fate determination, can transform CSCs into non-stem-like cancer cells." (PMID 32932969, 2020). "The lack of dependency on either YAP1 or WWTR1 in the non-dependent lines is intriguing, given the importance of these genes in most OSCC cancer cells." (PMID 32990596, 2020). "YAP1 is capable of reprogramming non-CSCs into cells that have CSC-like characteristics and helps cancer cells to maintain their stemness by promoting autophagy." (PMID 31137841, 2019). "We found total YAP1 expression and nuclear YAP1 expression indicated the unfavorable prognosis, both with OS and DFS, whereas the YAP1 expressed in cytoplasm was not related with cancer patients’ prognosis." (PMID 31613226, 2019). "Together this argues that YAP1 distal binding is a general feature of YAP1/TEAD-driven transcription activation also in non-transformed cells and is not an acquired feature of cancer cells." (PMID 26295846, 2015). "Our genome-wide analysis of YAP1/TEAD1 binding indicates that the vast majority of endogenous sites, in cancer and non-cancer cells (SF268, NCI-H2052 and IMR90), are actually located within distal regulatory regions representing enhancer elements." (PMID 26295846, 2015). "The results strongly supported that the expression of YAP1 and STK3 are significantly and positively correlated, no matter in primary samples or cancer cell lines, in mRNA or protein levels, in bulk scale or single cell scale, and in in-house or public databases." (PMID 40604818, 2025). "In cancers, TAZ, but not YAP1, acts as an oncogene to promote cancer progression." (PMID 36624516, 2023). "YAP1 activation and PTPN14 are relevant to both viral and nonviral cancers." (PMID 35170430, 2022). "While YAP1 activation is a major bypass mechanism to EGFR and MAPK pathway inhibition, the role of YAP1 as a mechanism of resistance to therapy seems to be general in many cancer types and independent of the type of treatment used." (PMID 34685695, 2021). "Thus, to date there is no conclusive data to establish the impact of YAP1 and fetal/embryonic conversion in CRC, and whether sublethal CT can directly impose specific adjustments to cancer cells." (PMID 35606354, 2022). "However, we did not observe direct interaction between ERK2 and YAP1 (data not shown), suggesting that ERK2 might indirectly regulate the decay of YAP1 in cancer cells, which will be further explored in our future study." (PMID 31848326, 2019). "However, it is still possible that other molecular events may control YAP activation in >65% of HNSCC cases that do not exhibit YAP1 or FAT1 genomic alterations, whose elucidation may help reveal new molecular mechanisms controlling the Hippo pathway in cancer." (PMID 34725466, 2021).
infection (27 papers, 2008 to 2025). The state of being infected such as from the introduction of a foreign agent such as serum, vaccine, antigenic substance or organism. "Deletion of the Yap1 oxidative stress response protein in Ustilago maydis caused avirulence on corn, resulting from an excess oxidative stress on infection structures." (PMID 19893627, 2009). "qRT-PCR analysis showed reduced YAP1/TAZ mRNA levels following a 72 h infection with shYAP1/shTAZ lentivirus." (PMID 38247878, 2024). "Of note, eleven TFs (Aft1, Ap5, Haa1, Hap4, Hap5, Msn4, Upc2, Yap1, Yap3, Yap6, and Yap7) are known to either bind or control some of the macrophage infection-induced genes as reported by PathoYeastract." (PMID 39356739, 2024). "Maintaining infection in basal cells is critical for HPV persistence, and here we demonstrate that YAP1 activation causes HPV E7 expressing cells to be retained in the basal compartment of stratified epithelia." (PMID 35170430, 2022). "The results indicated that circUBAP2 silencing significantly reduced the expression of YAP1 in OS cells, whereas the level of YAP1was upregulated following the infection with Anti-miR." (PMID 32528231, 2020). "We treated NMuMG-GFP (as infection control), NMuMG-HRas/shp53, and NMuMG-HRas/shp53/YAP1 cells with BSH (2 mM) or BSH-11R (10 μM) and performed immunofluorescent analyses using anti-BSH antibody." (PMID 32977522, 2020). "With Hp26695 infection, YAP1 protein expression in AGS, BGC‐823, and GES‐1 cells was upregulated in a time‐dependent manner, while YAP1S127 protein expression showed the opposite trend, indicating a potential increase in YAP1 nuclear translocation." (PMID 31145543, 2019). "In our study, we attempted to elucidate the mechanism by which Hp infection triggers GC and how GC cells transform infection signals into constant inflammation, revealing that YAP1 serves as the link." (PMID 31145543, 2019). "In both cell lines, Hp26695 infection significantly increased the colony formation ability, and this effect was inhibited by YAP1 knockdown." (PMID 31145543, 2019). "In the Hp infection study, both YAP1 and IL‐1β expression showed an infection time‐dependent trend, which provided a clue into the novel mechanism." (PMID 31145543, 2019). "The exogenous YAP1/IRF3 complex was more easily detected in HEK293 cells 6 h after infection with VSV." (PMID 31139191, 2019). "In M1 pro-inflammatory-like macrophages, m6A was found in transcripts that are highly expressed and translated during macrophage response to infection including TLR4 (Toll-Like Receptor 4), ICAM1 (Intracellular Adhesion Molecule 1) and YAP1 (Yes-associated protein 1)." (PMID 38780787, 2024). "Critically, targets of transcription factors known to regulate inflammation (IRF1, STAT1, STAT3) and fibrosis (SMAD2/3, EGR1, TEAD4, YAP1) appeared to be highly induced in the host, consistent with prior reports of infection-dependent induction of pro-inflammatory and pro-fibrotic gene expression." (PMID 36923592, 2023). "Furthermore, our data demonstrate that YAP-1/YAP and EGL-44/TEAD are required for resistance to infections with pathogenic bacteria when the intestinal barrier is disrupted in worms and mice." (PMID 32857822, 2020). "Finally, we found that the worms overexpressing yap-1p::yap-1::gfp were more resistant to infections with P. aeruginosa PA14 and S. Typhimurium than WT worms." (PMID 32857822, 2020). "Western blot analysis showed that infection with oe-lncARSR decreased YAP1, increased IRS2 expression and phosphorylation level of AKT, and did not affected AKT expression in oleate-treated cells, which was opposite in oleate-treated cells infected with sh-lncARSR." (PMID 32169080, 2020). "To facilitate isoform-specific characterization, we further subcloned these YAP1 cDNA into a lentiviral expression vector and generated, in YAP1-KO background, reconstituted expression of YAP1 isoforms by lentiviral infection with their relative expression confirmed by qRT-PCR." (PMID 32292505, 2020).